LEP (leptin)
Diseases named in the same sentence as LEP in open-access papers (continued):
Sharing a sentence is not in itself a finding about the gene and the disease.
Obesity (continued). "In addition, adipokines, leptin and adiponectin, play important roles in the pathophysiology of cancer associated with obesity." (PMID 27036040, 2016). "Obesity causes leptin resistance in the hypothalamus accompanied by hepatic steatosis in the liver." (PMID 27618865, 2016). "On the other hand, leptin which is frequently associated with obesity could also stimulate the proliferation of breast cancer cell lines as outlined in the previous studies." (PMID 27558166, 2016). "Obesity is associated with leptin resistance, and the trend for higher circulating levels of leptin in arsenic-exposed mice could be a potential mechanism that deserves further investigation." (PMID 26295903, 2016). "For example, leptin previously has been implicated to activate mTORC1 in obesity and cancer." (PMID 26908330, 2016). "It suggests that leptin is a better markerof fat mass value than resistin and may be considered an independent risk factor forcardiac disorders that is largely dependent on obesity." (PMID 27627223, 2016). "Moreover, an increase in food intake and obesity was observed in IRS-2-deficient mice despite their high circulating levels of leptin." (PMID 27812350, 2016). "Insulin and leptin are suggested links between obesity and breast cancer risk, as they may contribute to the malignant transformation of breast epithelial cells and cancer progression." (PMID 27415018, 2016). "Diet early in life might regulate leptin levels, which in turn will influence energy intake and risk of obesity." (PMID 27141948, 2016). "ob/ob mice exhibit obesity and diabetes-like syndromes because of spontaneous leptin mutation." (PMID 27942420, 2016). "However, it has been postulated that obesity is associated with increased levels of leptin and that a decrease in leptin’s anorexigenic effect via resistance mechanisms occurs in obese patients." (PMID 27408717, 2016). "A previous study indicates that offspring obesity is associated with abnormal expression of leptin." (PMID 26789724, 2016). "Leptin is involved in food intake, energy expenditure, and reproduction amongst many other functions, and is associated with several metabolic diseases, such as obesity." (PMID 26789724, 2016). "Regarding the metabolic consequences of the leptin surge at adulthood, it has been shown that its blockade by administration of a leptin antagonist predisposes adult rats to increased body weight gain, higher susceptibility to the development of obesity and leptin resistance." (PMID 27618559, 2016). "In addition, obesity is associated with increased expression of leptin with decreased expression of adiponectin." (PMID 27746742, 2016). "Another central pathway involving increased neuropeptide Y (NPY) arising from leptin resistance during obesity is implicated in bone metabolism as mice with increased central NPY have concurrent obesity with bone loss and NPY deficiency in ob/ob mice leads to improved cortical bone mass." (PMID 27512386, 2016). "The findings suggest that leptin is a better marker of fat mass value thanresistin and may be considered an independent risk factor for cardiacdisorders that is largely dependent on obesity." (PMID 27627223, 2016). "The LEP gene, encoded leptin that was associated with obesity and carcinogenesis." (PMID 27768592, 2016). "In addition to the increased activity of NPY neurons, Ngn3 mutants display a loss of Pomc expression in the ARC that is associated with postnatal obesity and a loss of leptin sensitivity." (PMID 27533310, 2016). "Hence, leptin resistance is considered to be one of the central causes of obesity, and a great deal of effort has been expended on understanding the nature of the state." (PMID 26849804, 2016). "The mechanisms, however, through which leptin acts at the DMH promoting obesity‐associated hypertension are still unknown." (PMID 27273815, 2016).
Obesity (continued). "Indeed, adiponectin, leptin and other mediators have been associated with obesity, but their association with the immune response of children with obesity shown in this paper is a new finding." (PMID 27977792, 2016). "In adult life, chronic exposure to leptin associated with obesity leads to resistance to the appetite-regulatory actions of leptin at the hypothalamus and it may be speculated that leptin insensitivity could arise in fetuses overexposed to leptin." (PMID 26479186, 2016). "In summary, our findings reveal a novel mechanism responsible for reduced lactation success in obesity, and they support a model in which high leptin levels are a possible cause of the peripheral and central prolactin resistance that is observed in obese animals." (PMID 26926925, 2016). "High serum leptin levels may play a relevant role in obesity-associated cardiovascular diseases including atherosclerosis." (PMID 28097156, 2016). "A possible contributor to obesity caused by AC3 ablation is leptin insensitivity." (PMID 27942392, 2016). "In several studies leptin is linked with OSAS independently of obesity." (PMID 25873773, 2015). "Moreover, increased leptin, hsCRP and TNFα concentrations were also risk factors for obesity (p < 0.05)." (PMID 25897330, 2015). "Consequently, the total plasma leptin level in this patient will be lowered: this is a clinically established risk factor of obesity." (PMID 26694100, 2015). "Leptin resistance is considered a primary risk factor for obesity." (PMID 25600821, 2015). "A recent study in Pakistani population indicated the association of this SNP with female obesity and proposed that the SNP may play its role by affecting plasma glucose and leptin levels." (PMID 26357660, 2015). "Collectively, available data indicate that a loss of beneficial leptin signaling can contribute to AD, suggesting that leptin resistance may be a mechanism by which obesity affects AD risk." (PMID 26217222, 2015). "As obesity-related proinflammatory response is associated with higher plasma leptin levels, we also assessed whether LEP DNA methylation levels in blood cells are associated with circulating levels of the pro-inflammatory CRP." (PMID 25929254, 2015). "The inhibition is significant at clinically relevant concentrations and could therefore serve as a new pathway to investigate to understand the molecular basis of leptin resistance, obesity and associated disorders." (PMID 25600821, 2015). "Both leptin and adiponectin are associated with obesity, IR and T2D." (PMID 25979814, 2015). "The potential mechanisms underlying the effect of obesity on IDD may include increased mechanical loading and atherosclerosis caused by obesity, however, the role of adipocytokines, and leptin in particular, in disc degeneration remains to be elucidated." (PMID 25892402, 2015). "Second, the significance of hypothalamic microglia and astrocytes in pathological metabolic processes associated with obesity, such as hypothalamic inflammation and related insulin and leptin resistance, has become increasingly evident in rodent and human disease models." (PMID 26491443, 2015). "The results here suggest that the inhibition of leptin secreted by obASCs may result in reduced tumor volume and metastasis to distant organs, reducing the burden of obesity-associated breast cancers." (PMID 26286584, 2015). "In addition to leptin, a further candidate re epigenetic regulation is that of the fat mass and obesity-associated (FTO) gene." (PMID 26402696, 2015). "In line with this, and taking into account that obesity is associated to suppressed GH release, it seems reasonable to propose that other factors (leptin, insulin, adipokines, inflammatory factors, etc.)should contribute to the increased gene expression of GH/IGF-1 axis components." (PMID 25806796, 2015).
Obesity (continued). "Obesity in their mouse model was associated with increased circulating leptin levels, and an increase in the orexigenic factor NPY in the hypothalamus, an observation that is consistent with our microarray data suggesting a deregulation of food intake control in the brain." (PMID 25629159, 2015). "Taken together, the results from this study show that leptin supplementation throughout lactation is able to revert the expression of most of the identified potential early biomarkers of programmed obesity risk and other metabolic alterations associated to undernutrition during pregnancy." (PMID 25766068, 2015). "There are few studies that associate obesity status with LEP G-2548A and LEPR Gln223Arg polymorphisms, and, even more important, these associations are shown in a racial dependent fashion; that is why it is necessary to determine their influence on obesity in Mexican population groups." (PMID 26064921, 2015). "Obesity is associated with chronically elevated leptin levels that may give rise to leptin resistance." (PMID 25835291, 2015). "Regarding the first hypothesis of changes in adipokine levels as the link between obesity and colon cancer, we investigated the influence of leptin by the use of leptin-deficient mice." (PMID 26347815, 2015). "However, common forms of obesity are typically associated with elevated leptin and resistance to effects of leptin on energy homeostasis." (PMID 26115673, 2015). "Indeed, loss of leptin or LepRb promotes obesity and decreases OX expression compared to normal weight animals." (PMID 25741247, 2015). "Interestingly, SH2B1 is known to be involved in leptin and insulin signaling and has been reported as a predisposing factor for obesity." (PMID 26293599, 2015). "Therefore, leptin is considered as one of the target molecules linking obesity and higher risk of cancer development." (PMID 25704884, 2015). "Obesity is currently regarded as a pro-inflammatory condition during which leptin (Ob gene product) might act as a risk factor for Cardiovascular Diseases (CVD) including Acute Myocardial Infarction (AMI)." (PMID 25762868, 2015). "Since leptin pathway mutations are a very rare condition in the human population, the continued exclusive use of these models will impede the studies of CNS mechanisms that are central to combating the obesity conditions in the human population." (PMID 25961053, 2015). "Obesity is associated with increased leptin levels, and leptin resistance may be a characteristic of obesity contributing to insulin resistance and lipotoxicity." (PMID 26244048, 2015). "Other molecules associated with obesity are leptin and adiponectin." (PMID 26380303, 2015). "Based on our results, inhibition of autophagy could impact leptin-induced tumor progression and further provoke new therapeutic strategies in obesity-associated cancer development." (PMID 25704884, 2015). "We then analyzed whether the signaling pathway associated with leptin plays a role in the obesity-related mitochondrial dysfunction observed in colon cancer." (PMID 26472027, 2015). "Indeed, the association of leptin with cancer and obesity, including colon cancer, has been previously studied by us and others." (PMID 26472027, 2015). "Several obesity-associated changes such as leptin resistance, hyperinsulinemia, excessive inflammation, and altered glucose metabolism which are required for the functionality of lymphocytes could affect the immune response." (PMID 25306890, 2015). "After injury, sympathetic tone diminishes, reducing the resting metabolic rate, which together with increased leptin levels could increase the risk of obesity." (PMID 25706982, 2015). "Association of leptin with endothelial dysfunction in obesity is known." (PMID 25658689, 2015). "Recessive mutations in the leptin gene are strongly associated with obesity in mice and humans." (PMID 26694100, 2015).
Obesity (continued). "The role of leptin on pancreatic cancer growth in vivo had previously been reported through experiments utilizing the LepDB (long form leptin receptor deficient) and LepOB (ligand deficient) mice that inherently develop obesity." (PMID 25919692, 2015). "Leptin-deficient ob/ob mice are a commonly used model of obesity/Type 2 diabetes." (PMID 25849138, 2015). "Leptin, which increases in proportion to obesity, has been associated with asthma in obesity." (PMID 26610598, 2015). "The hyperphagia, reduced metabolism, and increased fat mass of our cKO mice is comparable to other mouse models of obesity such as leptin- and leptin-receptor-deficient mice, that develop obesity from early age, and a maturity-onset mouse obese model in which the melanocortin system was targeted." (PMID 25629159, 2015). "As expected, leptin-deficient ob/ob mice exhibited severe obesity and hyperphagia." (PMID 26159457, 2015). "Similarly to obesity, leptin was shown to correlate with increased prostate cancer risk and developing of larger tumours, while the data linking leptin levels with prostate cancer incidence is inconclusive." (PMID 26376613, 2015). "To investigate more details about the association between Ppp2cα and insulin resistance in the liver, we first examined the expression of Ppp2cα in the livers of two mice models of obesity and type 2 diabetes, leptin-deficient ob/ob and high-fat diet (HFD) mice." (PMID 25888638, 2015). "However, their mutations compromise the leptin pathway which is essential for the normal function of CNS obesity and feeding behavior." (PMID 25961053, 2015). "After that, we analyzed all unannotated SNPs in the [-70; -20] region (where all proven TBP-binding sites are located) in the only known promoter of the human LEP gene, which we selected due to Friedman's discovery that the LEP gene (encodes hormone leptin) is the "obesity gene": OB ≡ LEP." (PMID 26694100, 2015). "In the Heart and Soul Study, low leptin was associated with 37% increased risk of cardiovascular events in patients with mean age of 67 years and stable coronary artery disease after adjusting for obesity and traditional cardiovascular risk factors." (PMID 26473487, 2015). "As an example, altered FTO methylation and gene regulation may provide a link between obesity-associated leptin resistance following IUGR and rapid postnatal weight gain." (PMID 26402696, 2015). "We observed that increased adipocyte size (a hallmark of obesity) was directly associated with leptin expression, angiogenesis (CD31) and lymphangiogenesis (podoplanin); however, these parameters were associated with nodal metastasis only in peritumoral but not distal adipose tissue of patients." (PMID 25857300, 2015). "We know that disruption of leptin signaling and leptin resistance plays a critical role in obesity, a major risk factor for morbidity and mortality, and obesity-related disease such as impaired glucose metabolism, cancer, and the development of cardiovascular disease." (PMID 26061745, 2015). "Obesity is associated with high levels of leptin production by adipocytes." (PMID 25946091, 2015). "However, prolonged increases in plasma leptin levels due to obesity cause leptin resistance, affecting both leptin access to hypothalamic neurons and leptin signal transduction within hypothalamic neurons." (PMID 26236282, 2015). "In addition, early postnatal leptin blockage increases susceptibility to diet induced obesity in rats whereas administration of leptin during the postnatal period reverses obesity in prenatally undernourished adult rats." (PMID 26029119, 2015). "Obesity is linked with chronic, subclinical inflammation characterized by elevated levels of circulating proinflammatory mediators produced by adipose tissue, such as leptin, TNF-alpha, and IL-6." (PMID 26508818, 2015). "Thus, it has been suggested that an abnormal profile of post-natal leptin concentrations are causative in the later development of an obesity-prone phenotype." (PMID 26561832, 2015).
Obesity (continued). "Obesity is also associated with a chronic inflammatory response, which is characterized by the activation of some pro-inflammatory signaling pathways and the abnormal production of adipokines such as leptin." (PMID 26699936, 2015). "In women, serum leptin may contribute to eGFR decline independently from obesity and diabetes mellitus, although a cause-effect relationship cannot be established due to the observational nature of our study." (PMID 25710704, 2015). "Given that obesity and diabetes have been associated with the development of numerous cancers, leptin may act as a link between metabolic disorders and cancer." (PMID 25948792, 2015). "Laboratory studies revealed that short sleep could increase ghrelin level and decrease leptin level in the human body, which may alter eating habits and eventually predispose weight gain and obesity in the future." (PMID 26446623, 2015). "The inhibition is significant at clinically relevant concentrations and could therefore serve as a novel pathway to investigate to understand the molecular basis of leptin resistance, obesity and associated disorders." (PMID 25600821, 2015). "Protective effects of leptin during the suckling period against later obesity may be associated with changes in promoter methylation of the hypothalamic POMC gene." (PMID 26402696, 2015). "Leptin, for instance, controls food intake and energy expenditure and is increased in obese subjects, whereas adiponectin has a protective role in the development of obesity-associated diseases and is decreased in serum of obese patients." (PMID 24427296, 2014). "The factors that are linked to the development of obesity include, among the others, energy intake and hyperinsulinemia; furthermore, adipokines as leptin and proinflammatory cytokines, as well as adiponectin, may contribute to renal injury." (PMID 25110685, 2014). "We initially identified a mutation in LEP which might be associated with severe obesity in Chinese individuals in our study." (PMID 24707501, 2014). "Our data also suggest that circulating leptin and adiponectin may mediate the link of triglycerides and obesity, respectively, to UCC and OVC risk." (PMID 25115836, 2014). "Leptin is encoded by the obesity (ob) gene on human chromosome 7q31.3." (PMID 25415449, 2014). "Importantly, basal and postprandial PP levels are blunted in obese mice and humans, and this observation has been implicated as possibly causing obesity in ob/ob leptin knockout mice." (PMID 26237477, 2014). "Desensitization to leptin is a hallmark finding in energy abundance-related obesity." (PMID 25309775, 2014). "Included in the effects of obesity is its association with a chronic low-grade state of inflammation as well as elevations in blood glucose and alterations in serum factors such as insulin, leptin, adiponectin, and insulin-like-growth factor (IGF)-1." (PMID 24804677, 2014). "Genetic predisposition to obesity associated to leptin (ob/ob mice) or leptin receptor (db/db mice) deficiencies appear to shape a microbiota specialized for enhanced dietary energy recovery with elevated abundance of Firmicutes and reduced abundance of Bacteroidetes compared with lean mice." (PMID 24733124, 2014). "Also in rats, the administration of a diet high in fructose diminishes leptin sensitivity and makes the animals susceptible to obesity, confirmed through increased weight gain when transferred to a high fat diet." (PMID 25211467, 2014). "Consequently, leptin deficiency leads to hyperphagia, resulting in severe obesity and hyperinsulinemia in human." (PMID 25144618, 2014). "Among them, mutations in the leptin gene (ob/ob mice) or in the leptin receptor gene (db/db mice, fa/fa rats), leading to the deficiency of the related proteins, produce extreme obesity in rodents as well as in humans, due to hyperphagia, decreased energy expenditure, and insulin-resistance." (PMID 25352831, 2014).